IL2 (interleukin 2)
Diseases named in the same sentence as IL2 in open-access papers (continued):
Sharing a sentence is not in itself a finding about the gene and the disease.
Hypertension (continued). "Our next objective of this study was to determine if blockade of IL-2 with basiliximab (Simulect), a chimeric monoclonal antibody that functions as an immunosuppressive agent, could reduce hypertension in RUPP rats by lowering ET-1 and improve pup weight by inhibiting activated NK cells." (PMID 33407826, 2021). "Further, by releasing IL-2 and TNF-α, O3 induces inflammation, which promotes hypertension, coronary ischemia, and the impairment of autonomic control in the lungs and in the circulation." (PMID 40559941, 2025). "Mercury-exposed citizens, especially those with hypertension, had significantly higher concentrations of inflammatory cytokines TNF-α, IL-2, IL-6 and anti-inflammatory cytokine IL-10 as compared to the unexposed population." (PMID 33083327, 2020). "Since IL-2 is elevated in RUPP rats, we hypothesized that the increase in IL-2 might be driving the hypertension and reduced fetal growth." (PMID 33407826, 2021). "Thus, the aim of this work was to determine the Th1/Th17 (IL-6, IL-2, TNF, IL-17 and IFN-γ) and Th2 (IL-4 and IL-10) serum profile in Venezuelan Chagasic patients stratified according amiodarone treatment, hypertension and arrhythmias." (PMID 28327099, 2017). "However, we do not know the effect of IL-2 on renal or placental mt dysfunction as a mechanism to improve hypertension." (PMID 34685775, 2021).
osteosarcoma (26 papers, 2011 to 2025). A usually aggressive malignant bone-forming mesenchymal neoplasm, predominantly affecting adolescents and young adults. "In a groundbreaking study involving canines with chemotherapy-resistant osteosarcoma metastases, the team administered intravenous infusions of cationic liposomes coupled with plasmid DNA encoding canine interleukin-2 (IL-2) cDNA." (PMID 38140058, 2023). "In another study, treatment with the Salmonella encoding IL-2 gene demonstrated a reduced osteosarcoma pulmonary metastasis associated with considerable increase of pulmonary NK cell population." (PMID 34829795, 2021). "Oral administration of the Salmonella encoding IL-2 gene has been subjected to phase 1 clinical study for canine osteosarcoma." (PMID 34829795, 2021). "IL-2 administration was also reported to increase the effectivity of autologous osteosarcoma-cell-derived vaccination in dogs." (PMID 37515069, 2023). "This was also shown in other studies that utilized Salmonella carrying IL-2 gene for the treatment of murine osteosarcoma and melanoma." (PMID 34203478, 2021). "For example, in one study IL-15 stimulated NK cells targeted osteosarcoma predominantly through DNAM1, whereas in another study IL-2 stimulated NK cells targeted osteosarcoma predominantly through NKG2D." (PMID 34164452, 2021). "Although evidence of IL‐2 efficacy in patients with osteosarcoma is limited, a recent prospective study of 35 unselected pediatric patients treated surgically for primary and metastatic osteosarcoma between 1995 and 2010 revealed promising results." (PMID 33152115, 2021). "The overall and 3‐year event‐free survival rates were 45% and 34%, respectively, suggesting a potential role for IL‐2 in the treatment of osteosarcomas." (PMID 33152115, 2021). "One more example used zoledronate, tested for use in osteosarcoma as an antitumor drug, but the efficacy was very low, though use with IL-2 reportedly stimulated γδ T-cells in an orthotopic mouse model of osteosarcoma." (PMID 32664248, 2020). "After IL-2 administration and polychemotherapy, osteosarcoma patients had increased numbers, and increased activity, of NK cells in the blood, the magnitude of which strongly correlated with the clinical outcomes." (PMID 31156651, 2019). "A study of high-dose IL-2 in relapsed pediatric patients included four patients with osteosarcoma and two patients with Ewing sarcoma." (PMID 26301204, 2015). "More recently, however, high-dose IL-2 was given in a pediatric population including several patients with osteosarcoma." (PMID 21331153, 2011). "IL-2 activates lymphocytes into lymphokine-activated killer (LAK) cells, effective against multidrug-resistant cells and targeting lung metastasis sites, underlining the potential of IL-2 and LAK/NK cell-based therapies in managing pediatric osteosarcoma lung metastases." (PMID 39911380, 2025). "Importantly, IL-2 aerosolization in dogs and mice with osteosarcoma lung metastasis similarly enhanced the local proliferation and cytotoxicity of NK cells and induced metastatic regression." (PMID 31156651, 2019). "Cytokines, such as GM-CSF, IL-2, and IFN-α, are clinically validated therapeutic strategies for the treatment of osteosarcoma." (PMID 39742319, 2025). "The recent adoptive T-cell transfer in the canine osteosarcoma trial also combined ACT with a tumor vaccine and IL-2 injection." (PMID 38668417, 2024). "In a clinical trial using IL-2 with or without reinfusion of LAK for patients with metastatic osteosarcoma, 3-year event-free and overall survival rates were 34% and 45%, respectively." (PMID 30693030, 2019). "Based on the results of past studies, IFN-α and IL-2 can activate antitumor immune responses, although no significant improvement in osteosarcoma treatment outcomes has been observed in the previous trials." (PMID 30693030, 2019).
osteosarcoma (continued). "Therefore, we evaluated the efficacy of bempegaldesleukin (BEMPEG; NKTR‐214), a first‐in‐class CD122‐preferential IL‐2 pathway agonist, alone and in combination with anti‐PD‐1 or anti‐CTLA‐4 immune checkpoint inhibitors in metastatic and orthotopic murine models of osteosarcoma." (PMID 33152115, 2021). "The addition of immunomodulatory cytokines such as IL2, IL15, and liposomal-muramyl tripeptide phosphatidylethanolamine might induce T cell proliferation and differentiation to improve the survival outcomes of osteosarcoma patients, but the evidence is insufficient." (PMID 35720360, 2022).
ulcerative colitis (26 papers, 2009 to 2025). An inflammatory bowel disease involving the mucosal surface of the large intestine and rectum. "We demonstrated that the human IL-2 covalently modified by anti-human IL-2 antibody suppresses the cellular and humoral immunity and controls the disease progression in animal models of ulcerative colitis (UC) and SLE." (PMID 38461332, 2024). "One MPTP-treated group from each strain was treated with tacrolimus (FK506), a calcineurin/NFAT inhibitor that suppresses T-lymphocyte signal transduction pathways and IL2 transcription and is indicated for organ transplantation and ulcerative colitis." (PMID 34090462, 2021). "It has also been shown that IL-1β and IL-2 production is significantly increased in active ulcerative colitis and is significantly correlated to its activity index." (PMID 23497090, 2013). "Also, T lymphocytes and peripheral blood mononuclear cells responded to ERS by activating the IRE1/XBP1 signaling pathway, promoting secretions of IFN-γ, IL-17A, and IL-2 in a study about ulcerative colitis." (PMID 33933165, 2021). "Furthermore, in mice, targeted disruption of a gene similar to IL-2 leads to ulcerative colitis-like disease." (PMID 34815430, 2021). "In addition, patients with ulcerative colitis presented decreased levels of IL-2, IL-5 and MIP-1β after 21 days of consumption compared placebo group." (PMID 32714320, 2020). "In addition, low doses of IL-2 are used for the treatment of moderate to severe ulcerative colitis." (PMID 36432588, 2022). "Olsalazine significantly increased the contents of IL-2, IL-10, IL-22, TGF and EGF in ulcerative colitis rats, and significantly decreased the scores of DAI, CMDI, HS and the contents in IL-7, IL-17, TNF-α, IL-1β and IFN-γ when compared with the model group." (PMID 37610966, 2023). "It was suggested that olsalazine has a therapeutic effect on ulcerative colitis induced by DSS in mice, and the mechanism may be related to the increase of IL-2, IL-10, IL-22, TGF, and EGF and the decrease of the expression of IL-7, IL-17, TNF-α, IL-1β, and IFN-γ." (PMID 37610966, 2023). "The promise of IL-2 mutein in human disease is now being realised after safety and dose finding studies supported the progression to a pioneering clinical trial of PT101 IL-2 mutein complex in patients with active ulcerative colitis (ClinicalTrials.gov NCT04924114)." (PMID 35641679, 2022).
autoimmune hepatitis (25 papers, 2014 to 2025). Hepatitis caused by autoantibodies. "With autoimmune hepatitis associated with Con A, the serum levels of some inflammatory cytokines (IL-2/4/10, IFNγ and TGF-β) were altered to varying degrees." (PMID 30356792, 2018). "A few clues suggest an association between IL-2 signal deregulation and autoimmune liver diseases." (PMID 31616649, 2019). "While IL-2’s benefits for autoimmune liver disease remain to be fully explored, animal models of autoimmune hepatitis and primary sclerosing cholangitis have indicated its potential to improve biochemical markers and reduce bile duct damage." (PMID 38408917, 2024). "Other publications in pediatric autoimmune hepatitis also detected minor differences between groups and showed how IL-2 levels predicted treatment response." (PMID 39199571, 2024). "Recombinant IL-2 (aldesleukin) has been utilised in a wide range of autoimmune conditions to date including autoimmune liver diseases AIH and PSC." (PMID 35641679, 2022). "Two patients with refractory autoimmune hepatitis had been treated with monthly 5-day cycles of low-dose IL-2 therapy for 6 month in a compassionate use setting." (PMID 33868284, 2021). "The effectiveness of IL-2 therapy in liver disease has been investigated in animal models and human subjects with autoimmune liver disease." (PMID 34721383, 2021). "Pretreatment with resveratrol ameliorated the pathologic effects of ConA-induced autoimmune hepatitis and significantly inhibited IL-2, IL-6, TNF-α, Shh, Gli-1, and Ptc." (PMID 26089871, 2015). "Recently, studies have reported that Con A-induced autoimmune hepatitis is largely mediated by the release of inflammatory cytokines such as IL-2, IL-4, IL-6, IL-10, IL-12, TNF-α and IFN-γ." (PMID 24498418, 2014). "Regarding emerging therapies being studied in autoimmune hepatitis, the most prominent themes we identified in our literature search relate to the balance between T cell activation, which can lead to production of IL-2 and IL-17, and suppressive responses, namely, the function of Tregs." (PMID 41585412, 2024). "Indeed, in vitro studies stimulating PBMCs or liver infiltrating lymphocytes from patients with autoimmune liver diseases with low doses of IL-2 showed improved survival and function of Foxp3+ TREG." (PMID 34463867, 2021). "We aimed to determine whether resveratrol could inhibit the expression and release of cytokines such as TNFα, IL-2, and IL-6 in ConA-induced autoimmune hepatitis." (PMID 26089871, 2015). "Pretreatment with ethyl pyruvate ameliorated the pathological effects of Con A-induced autoimmune hepatitis and significantly decreased the levels of TNF-α, IL-2, IL-6 and IL-1β at 3h and 6h and the level of HMGB1 at 6h and 24h post injection." (PMID 24498418, 2014). "Taken together, these results indicated that ethyl pyruvate protected against Con A-induced autoimmune hepatitis by decreasing both early (TNF-α, IL-2, IL-1β and IL-6) and late (HMGB1) cytokine expression in mice." (PMID 24498418, 2014). "IL-2, IL-6, TNF-α and IL-1β were released starting at 3h after administration of Con A, and inhibition of the release of these cytokines attenuates the Con A-induced autoimmune hepatitis." (PMID 24498418, 2014). "The purpose of our study was to determine whether ethyl pyruvate could inhibit the expression and release of both early (TNF-α, IL-2, IL-6, IL-1β) and late (HMGB1 ) cytokines in Con A-induced autoimmune hepatitis." (PMID 24498418, 2014). "To establish the potential of IL‐2 to enhance Treg therapy, we investigated the effects of very low dose Proleukin (VLDP) on the phosphorylation of STAT‐5 and the subsequent survival and function of Treg and T effector cells from the blood and livers of patients with autoimmune liver diseases." (PMID 28176332, 2017). "The importance of IL‐2 for Treg function has not been studied closely in autoimmune liver diseases." (PMID 28176332, 2017).
ischemic heart disease (25 papers, 2010 to 2025). "Subsequently, increased levels of IL-2 were associated with adult patients with coronary artery disease and CIMT." (PMID 40426748, 2025). "Our results are consistent with the findings of a recent study conducted by Ding et al28, which revealed the association of IL-2-330 GG genotype with increased risk of coronary artery disease." (PMID 30090212, 2018). "Low-dose interleukin-2 (IL-2LD) selectively increases regulatory T (Treg) cell numbers in patients with coronary artery disease." (PMID 40461772, 2025). "Previous clinical studies of low-dose IL-2 therapy in patients with ischemic heart disease have demonstrated enhanced Treg responses and cardioprotective effects." (PMID 41291938, 2025). "Recently, the safety of low-dose interleukin-2 administration in patients with ischemic heart disease was evaluated in a clinical trial." (PMID 39549205, 2024). "The LILACS (Low-Dose Interleukin-2 in Patients With Stable Ischemic Heart Disease and Acute Coronary Syndromes) study demonstrated significant Treg expansion without adverse events in patients with stable or unstable ischemic heart disease." (PMID 39766344, 2024). "Another avenue that is currently being explored is the use of low-dose aldesleukin, a recombinant IL-2, in patients with stable ischemic heart disease to specifically stimulate Tregs." (PMID 39161593, 2024). "So far, only 1 phase I/II clinical Treg trial is registered in which IL-2 is used to increase Treg cell numbers to assess safety of and efficacy of IL-2 to increase circulating Treg levels by 75% in patients with ischemic heart disease." (PMID 38093747, 2023). "IL2RB, a receptor for IL-2, is involved in T cell-mediated immune responses and plays a fundamental role in the development of coronary artery disease." (PMID 38104081, 2023). "Here, a human recombinant form of IL-2, aldesleukin (Proleukin®, Novartis), is administered in varying low-dose strategies to patients with stable ischemic heart disease and acute coronary syndromes." (PMID 33266027, 2020). "A current on-going investigation is the LILACS (low-dose interleukin-2 in patients with stable ischemic heart disease and acute coronary syndromes) trial." (PMID 33266027, 2020). "Given the importance of cytokines in the context of the failing heart, the prevalence of Interleukin-2 (IL-2) and Interferon-gamma (IFN-γ) polymorphisms was studied in patients with CHF due to ischemic heart disease in a case-control study." (PMID 30090212, 2018). "However, further research is required to confirm the safety and evaluate the effectiveness of low-dose interleukin-2 as an anti-inflammatory treatment for individuals with ischemic heart disease." (PMID 39549205, 2024). "Importantly, IL2RB mainly combines with IL2 to play a key role in coronary heart disease (CHD) development, which indicates that it also plays a role in cardiovascular-related immune-inflammatory diseases." (PMID 35924269, 2022). "Another interesting, alternative approach to achieve atheroprotective immune modulation was the LILACS trial (Low-Dose Interleukin-2 in Patients with Stable Ischemic Heart Disease and Acute Coronary Syndromes) that aimed to study the effect of increasing Treg cells by treatment with low dose IL-2." (PMID 35269559, 2022). "The randomized, double-blind, placebo-controlled LILACS trial (NCT03113773) examined whether solely administering low-dose IL-2 is safe and effective in patients with stable ischemic heart disease and acute coronary syndrome." (PMID 35097027, 2021). "The expansion of Treg cells by the IL-2 complex may be a potentially valuable approach to improving ischemic heart disease." (PMID 27144181, 2016). "This indicates that low-dose IL-2 may have potential to treat ischemic heart disease." (PMID 40260235, 2025). "Indeed, humans with DCM and CHF have increased circulating IL-2 concentrations, a finding which is not consistently observed in individuals with coronary artery disease." (PMID 41284707, 2025).